BRAF (B-Raf proto-oncogene, serine/threonine kinase)
Diseases named in the same sentence as BRAF in open-access papers (continued):
Sharing a sentence is not in itself a finding about the gene and the disease.
metastatic melanoma (continued). "The landscape of metastatic melanoma treatment has evolved strikingly in recent years with the development of antitumor molecular targets, including BRAF-inhibitors such as vemurafinib and dabrafenib and MEK-inhibition with trametinib." (PMID 25932372, 2015). "LMD remains a devastating complication of cancer despite the significant improvement in overall survival of patients with metastatic melanoma with new effective systemic treatments, including selective BRAF inhibitors and anti-CTLA-4 antibody." (PMID 25962795, 2015). "Mutations in BRAF, NRAS, and KIT are known to be involved in the pathogenesis of metastatic melanoma." (PMID 26136771, 2015). "Pretreatment samples from 76 patients with BRAFV600E-positive metastatic melanoma who were treated with the BRAF inhibitors vemurafenib (n = 67) or dabrafenib (n = 9) were retrospectively analyzed by NGS." (PMID 26498143, 2015). "On September 4, 2014, the US FDA approved pembrolizumab for the treatment of patients with unresectable or metastatic melanoma with disease progression after treatment with ipilimumab or BRAF-inhibitor in case of BRAF-positive disease." (PMID 26171394, 2015). "In a small fraction of metastatic melanoma (about 15% of cases), however, CCND1 amplification and BRAF mutations are coexisting and confer resistance to treatment with BRAF inhibitors." (PMID 26322273, 2015). "In December 2014, nivolumab became the second monoclonal antibody targeting the PD-1 receptor to be approved by FDA for the treatment of patients with unresectable or metastatic melanoma and disease progression following ipilimumab and a BRAF inhibitor." (PMID 26419843, 2015). "GSK2118436 (Dabrafenib) another ATP competitive BRAF inhibitor, has recently shown a dramatic effect as single agent in patients with metastatic melanoma and other solid tumours, and is currently under a phase I/II clinical trial." (PMID 25361007, 2014). "The inhibitors of mutant BRAF that are used to treat metastatic melanoma induce squamoproliferative lesions." (PMID 25360634, 2014). "A patient with BRAF(L597S)-mutant metastatic melanoma responded significantly to treatment with the MEK inhibitor TAK-733." (PMID 24743024, 2014). "The immunosuppressant azathioprine, the fluoroquinolone antibiotics and vemurafenib—a BRAF inhibitor used to treat metastatic melanoma—are all recognized clinical photosensitizers." (PMID 25414333, 2014). "Preclinical studies of vemurafenib (PLX4032), a potent oral small molecule inhibitor of mutated BRAF, have culminated in a phase III RCT of vemurafenib versus dacarbazine in 675 patients with BRAF-mutated metastatic melanoma." (PMID 25610709, 2014). "The clinical use of BRAF inhibitors for treatment of metastatic melanoma is limited by the development of drug resistance." (PMID 24735930, 2014). "Given the evidence in murine models that low PTEN and BRAF V600 mutations results in development of metastatic melanoma, we conducted an exploratory analysis based on PTEN mRNA expression and BRAF/NRAS status." (PMID 24830350, 2014). "For instance, the pharmacological inhibition of MEK (the downstream target of BRAF) improves overall survival in patients with BRAF-mutant metastatic melanoma, when compared with chemotherapy." (PMID 25594040, 2014). "Here we report a case of a 59-year-old woman with a diagnosis of BRAF-mutant metastatic melanoma that responded to initial treatment with vemurafenib." (PMID 25501056, 2014). "In other case report, Seghers et al6 demonstrated 2 patients with BRAF-mutant metastatic melanoma who progressed after treatment with dabrafenib/trametinib and dabrafenib, respectively." (PMID 25501056, 2014). "Selective inhibitors of BRAF, vemurafenib and dabrafenib are the standard of care for metastatic melanoma patients with BRAF V600, while chemotherapy continued to be widely used in BRAF wild type patients." (PMID 25437182, 2014).
metastatic melanoma (continued). "In recent years, 2 significant advances in the treatment of metastatic melanoma have emerged: the use of BRAF targeted therapy and immune checkpoint blockade." (PMID 25941608, 2014). "This concept was next studied in patients with BRAF-mutant metastatic melanoma by performing pre-treatment (day 0) and on-treatment (day 10–14) tumor biopsies." (PMID 29250602, 2014). "We report a case of a BRAF-mutant metastatic melanoma patient who responded to initial treatment with vemurafenib." (PMID 25501056, 2014). "One targeted therapy is vemurafenib, which was approved by the US Food and Drug Administration in August 2011 for the treatment of patients with unresectable or metastatic melanoma with BRAF V600E." (PMID 25120707, 2014). "We tested the mRNA and protein expression of BCL-2 family members in tumor samples from patients with metastatic melanoma 10–14 days into treatment with a BRAF inhibitor." (PMID 24983357, 2014). "Recently, Romano et al5 reported a case of a patient with BRAF-mutant metastatic melanoma retreated with vemurafenib." (PMID 25501056, 2014). "MAPK inhibitors (MAPKi) are active in BRAF-mutant metastatic melanoma patients, but the extent of response and progression-free survival (PFS) is variable, and complete responses are rare." (PMID 24400126, 2014). "The combination of vemurafenib and the MEK inhibitor cobimetinib (GDC-0973) has been tested in a phase I trial with BRAF positive metastatic melanomas." (PMID 25361007, 2014). "While BRAF-inhibitors such as vemurafenib have produced impressive response rates of approximately 60–80% in patients with BRAF-mutant metastatic malignant melanoma, vemurafenib is apparently much less efficient in BRAF-mutant CRC [21, meeting abstract]." (PMID 25309914, 2014). "The cost per QALY gained for treatment of BRAF+ metastatic melanoma with vemurafenib alone or in combination exceeds widely-cited thresholds for cost-effectiveness." (PMID 25198196, 2014). "Most patients with metastatic melanoma have early response with BRAF inhibitors as monotherapy, but acquired resistance frequently develops and the majority of patients experience relapse with a median of 6-7 months." (PMID 24735930, 2014). "We therefore sought to examine the patterns of response and progression to targeted therapy by measuring every metastasis ≥5 mm via computed tomography (CT) in a cohort of patients with metastatic melanoma treated with combined BRAF and MEK inhibitors." (PMID 24400126, 2014). "The selective BRAF inhibitor (BRAFi) vemurafenib is highly effective in treating metastatic melanomas and has been approved as a first-line therapeutic for metastatic melanoma cases that harbor V600 mutations in BRAF." (PMID 25360634, 2014). "The revolutionary discovery of a striking, if temporary, effect that targeted inhibition of BRAF has on the clinical course of metastatic melanoma has spiked a new wave of research into molecular targets." (PMID 24743024, 2014). "Recently, drugs targeting the constitutively active BRAF protein such as vemurafenib and immunotherapies such as ipilimumab were licensed for patients with metastatic melanoma (MM)." (PMID 24455677, 2013). "Increased MART, TYRP-1, TYRP-2, and gp100 expression was found in metastatic melanoma specimens obtained from patients after treatment with BRAF and/or MEK inhibition." (PMID 24194739, 2013). "Activating mutations in the BRAF (V600E) and NRAS (Q61K) genes are found at a frequency of 40–60 and 15–30 % in metastatic melanomas, respectively." (PMID 23673558, 2013). "Recently, selective BRAF inhibitors such as PLX4032 (vemurafenib) and GSK2118436 (dabrafenib) have shown clinical efficacy in BRAF mutant metastatic melanoma patients with significant tumor regression in approximately 60% of patients." (PMID 23750336, 2013). "A current limitation of targeted therapies against metastatic melanoma with BRAF or MEK inhibitors is the development of resistance." (PMID 23890105, 2013).
metastatic melanoma (continued). "Our repeated observation is that patients with metastatic melanoma who are treated systemically with BRAF inhibitors show remission of extracerebral metastases, but development or progression of brain metastases." (PMID 24133630, 2013). "More recently, greater improvements have been noted in metastatic melanoma patients treated with combination targeted therapies, particularity so the combination of BRAF (Dabrafenib) and MEK (Trametinib) inhibitors." (PMID 23515890, 2013). "The cobas 4800 BRAF V600 Mutation Test is a CE-marked and FDA-approved in vitro diagnostic assay used to select patients with metastatic melanoma for treatment with the selective BRAF inhibitor vemurafenib." (PMID 23326492, 2013). "Treatment with combined BRAF and MEK inhibition in V600 BRAF mutation-positive metastatic melanoma has been evaluated in phase I and II clinical trials." (PMID 24276125, 2013). "While the response rate of patients with BRAF V600E mutant metastatic melanoma to oral BRAF inhibitor vemurafenib is high, the median overall survival is approximately sixteen months." (PMID 23418523, 2013). "In a phase II study that set out to investigate a selective BRAF inhibitor, vemurafenib, in patients with metastatic melanoma, 6% had a complete response and 47% had a partial response to the agent." (PMID 23420786, 2013). "A quite similar frequency of either BRAF or NRAS mutations was observed among primary and metastatic melanomas: 49% vs. 51%, for BRAF, and 15% vs. 16%, for NRAS, respectively." (PMID 23987572, 2013). "Currently a phase I/II clinical trial (NCT01400451) combining BRAF targeted therapy (Vemurafenib) with immunotherapy (Ipilimumab) is underway in subjects with BRAFV600E/K metastatic melanoma as a strategy to prolong PFS." (PMID 23515890, 2013). "A total of 156 patients with metastatic melanoma were involved in the study; 3 of these patients were BRAF wild-type with the other 153 presenting with various BRAFV600 mutations." (PMID 23515890, 2013). "The BRAF inhibitor vemurafenib was recently approved by the FDA for BRAF-mutant metastatic melanomas." (PMID 24047116, 2013). "Treatment of metastatic malignant melanoma patients harboring BRAF(V600E) has improved drastically after the discovery of the BRAF inhibitor, vemurafenib." (PMID 24023633, 2013). "Very high response rates and improved survival have been noted with the administration of the type I BRAF inhibitor vemurafenib (formerly PLX4032/RG7204) to patients with BRAFV600E mutant cutaneous metastatic melanoma." (PMID 22515704, 2012). "In metastatic melanoma new treatment options have recently emerged targeting BRAF or CTLA-4 showing improved overall survival, but these treatments are associated with significant toxicities and costs." (PMID 22719881, 2012). "BRAF inhibitors such as vemurafenib are a new family of biological drugs, recently available to treat metastatic malignant melanoma." (PMID 22846499, 2012). "We have examined the utilisation of these three signalling pathways in a number of cell lines derived from patients with metastatic malignant melanoma of known PIK3CA, PTEN, NRAS and BRAF mutational status." (PMID 22475322, 2012). "Consistent with these in vitro results, they also observed high IGF-1R and phosphorylated Akt in post-relapse tumour biopsies from patients whose metastatic melanoma developed resistance to BRAF inhibition." (PMID 23039341, 2012). "NCT01072175 is a clinical trial with the Raf inhibitor GSK2118436 in combination with the MEK Inhibitor GSK1120212 in metastatic melanoma patients containing mutant BRAF gene." (PMID 23085539, 2012). "This was demonstrated recently by the specific inhibitor of mutated BRAF, vemurafenib (PLX-4032), which produced a dramatic response in patients with BRAF-mutant metastatic melanoma, albeit tempered by the rapid emergence of resistance." (PMID 23039341, 2012).
metastatic melanoma (continued). "Ipilimumab (anti-CTLA4 antibody) and Vemurafenib (V600 mutant BRAF inhibitor) were approved for systemic treatment of metastatic melanoma." (PMID 29147288, 2012). "New targeted agents directed against the RAS-RAF-MEK-ERK pathway show promising activity in early clinical development and particular interest is focused on selective inhibitors of mutant BRAF, which is present in one half of the cases of metastatic melanoma." (PMID 21139585, 2011). "In a phase-I clinical trial enriched for patients with mutant BRAF metastatic melanoma 11/16 (68%) achieved partial response (PR) and four patients had minor responses leading to a progression-free survival (PFS) of 8–9 months." (PMID 21139585, 2011). "With exciting results demonstrated in the registration study against dacarbazine in metastatic melanoma, the use of oncogenic BRAF inhibitors such as vemurafenib in the adjuvant setting has been raised." (PMID 22220281, 2011). "These combination regimens are now the standard for treating BRAF-mutant metastatic melanoma." (PMID 40861441, 2025). "Patients treated with immunotherapy, targeted therapy, or combined targeted therapy with BRAF inhibitors had significantly better OS than patients treated with standard metastatic melanoma treatment options, e.g., local radiotherapy and/or chemotherapy, before December 2016." (PMID 40564879, 2025). "Trastuzumab and pertuzumab target different domains of the HER2 receptor and form a standard treatment for HER2-positive breast cancer, while BRAF and MEK inhibitors are co-administered to treat BRAF-mutated metastatic melanoma, improving outcomes and reducing toxicity." (PMID 41332727, 2025). "In addition to their use in metastatic melanoma, BRAF and MEK inhibitors have also been explored in the adjuvant setting." (PMID 40861441, 2025). "In a trial involving patients with metastatic melanoma, treatment with either a BRAF inhibitor (vemurafenib) or a BRAF/MEK inhibitor combination (dabrafenib and trametinib) experienced a significant increase in CD8+ T lymphocyte infiltration, as confirmed by tumor biopsy." (PMID 40564107, 2025). "Lifileucel, an autologous tumor-infiltrating lymphocyte (TIL) therapy, received accelerated FDA approval in 2024 for the treatment of patients with unresectable or metastatic melanoma who had previously progressed on PD-1 inhibitors and, if applicable, BRAF-targeted therapies." (PMID 40940995, 2025). "MC1R variants may also impact treatment outcomes: metastatic melanoma patients with concurrent BRAF V600 mutations and MC1R variants experienced lower response rates and shorter PFS on BRAF inhibitor therapy." (PMID 40981345, 2025). "Therefore, both treatments were valid first-line treatment options for BRAF mutant metastatic melanoma." (PMID 40362630, 2025). "Although metastatic melanoma still carries substantial mortality rates, targeted therapy involving BRAF/MEK inhibition and immunotherapy utilizing PD-1/PD-L1 inhibitors along with CTLA-4 inhibitors has led to remarkable advancements in treatment outcomes and prognosis improvement." (PMID 40331942, 2025). "Anti PD-1 antibodies, either as monotherapy or in combination with anti-CTLA-4 ones, should be considered first-line treatment for all patients with unresectable metastatic melanoma and independent of tumor BRAF mutational status." (PMID 38201012, 2024). "Although metastatic melanoma patients treated with BRAF + MEK inhibitors at our center were included in the study without selection, confounding variables may remain hidden due to the single-center study design." (PMID 39272837, 2024). "Programmed cell death protein 1 (PD-1) inhibitors are foundational therapeutics in the treatment of metastatic melanoma, and assessment of BRAF V600E/V600K ctDNA levels in patients receiving anti-PD-1 treatment has been shown to be an accurate predictive factor for tumor response, PFS, and OS." (PMID 39156972, 2024).
metastatic melanoma (continued). "This was a phase 1 clinical study in which V600 BRAF mutant metastatic melanoma patients, who were receiving concurrent treatment using the standard BRAF/MEK inhibitor combination of dabrafenib and trametinib, received intravenous infusions of GD2-iCAR-PBT products." (PMID 38754916, 2024). "Metastatic melanoma, a deadly form of skin cancer, often develops resistance to the BRAF inhibitor drug vemurafenib, highlighting the need for understanding the underlying mechanisms of resistance and exploring potential therapeutic strategies targeting integrins and TGF-β signalling." (PMID 39063187, 2024). "We performed a retrospective single institution analysis of 40 metastatic melanoma patients receiving combined BRAF/MEK inhibitors after progression on an anti-PD-1 or ipilimumab plus nivolumab to assess response rate by RECIST 1.1, progression-free and overall survival (PFS and OS)." (PMID 37971411, 2024). "Prospective and between trial comparisons indicate that first-line treatment with immune checkpoint inhibitors improves survival outcomes compared to first-line therapy with combined BRAF and MEK inhibitors in metastatic melanoma containing BRAFV600E/K mutations." (PMID 37971411, 2024). "Metastatic pattern and pretreatment LDH level have also been shown to be independent prognostic factors in other retrospective studies analyzing survival data in BRAF V600 mutant metastatic melanoma patients treated with first-line immune checkpoint inhibitors or BRAF + MEK inhibitors." (PMID 39272837, 2024). "In BRAF-mutated metastatic melanoma and EGFR-mutated advanced non-small cell lung cancer (NSCLC), small molecule inhibitors targeting BRAF or EGFR, respectively, significantly increased the overall survival and have become the standard of care in these patients." (PMID 39272879, 2024). "DTIC is an FDA-approved antineoplastic alkylating agent effective against metastatic melanoma, regardless of the presence of the BRAF mutation." (PMID 38338893, 2024). "We next sought to use this setup to identify the BRAF status of a panel of cell lines (Mel25, Mel28, Mel78, Mel79, Mel84, and Mel88) with unknown genotypes, derived from metastatic melanoma biopsies." (PMID 39644903, 2024). "Our study suggests that clinicopathological factors, including primary tumor characteristics, stage of metastatic disease, and serum LDH and S100B, can be used in the prognostic stratification of metastatic melanoma patients treated with BRAF and MEK inhibitors." (PMID 39272837, 2024). "These 4-year follow up data from the randomized, phase II SECOMBIT trial continue to demonstrate meaningful survival benefit with immunotherapy with or without an 8-week course of targeted therapy for the first-line treatment of BRAF-mutant metastatic melanoma." (PMID 38167503, 2024). "Robert, Caroline team found that nivolumab significantly improved overall and progression-free survival compared to dacarbazine in previously untreated patients with metastatic melanoma without BRAF mutations." (PMID 37152956, 2023). "Besides choosing either of two main treatment strategies for patients with BRAF-mutant metastatic melanoma, clinical research addresses new questions regarding the appropriateness of combination or sequential use of immune and targeted therapy." (PMID 36995534, 2023). "However, TTs lack durable responses and it was recently demonstrated that first-line nivolumab–ipilimumab followed by BRAF/MEK-inhibition on progression had the most favorable OS in metastatic melanoma." (PMID 36900253, 2023). "Improved progression-free survival resulted in the FDA approving the treatment of recurrent or metastatic melanoma as a first-line treatment, irrespective of BRAF V600 mutation status." (PMID 36765809, 2023). "Genetic interaction studies in genetically engineered mouse models showed that BRAF V600E expression cooperates with Pten tumor suppressor loss to generate metastatic melanoma without CNS involvement." (PMID 37920169, 2023).